IL10 (interleukin 10)
Diseases named in the same sentence as IL10 in open-access papers (continued):
Sharing a sentence is not in itself a finding about the gene and the disease.
COVID-19 (continued). "It has been demonstrated that there is a dramatic increase in IL-10 expression in the COVID-19 cytokine storm, which is thought to be a fundamental function for suppressing inflammation." (PMID 36329841, 2022). "We found that fatal COVID-19 was associated with higher levels of IL6, IL10, IL22, CXCL10, CCL2, and CCL20 and lower levels of miR-495-3p, miR-451a, and miR-29b-3p." (PMID 34957382, 2022). "In conclusion, we showed that patients with NAFLD have a different immune response to severe COVID-19, with IL-6, IL-8, IL-10, and CXCL10 as a possible culprits of an uncontrolled inflammation associated with disease severity in this group of patients." (PMID 35743825, 2022). "In the primary infection COVID-19 patient cohort, several plasma proteins increase with COVID-19 disease severity, including IL-6, IL-8, IL-10, IL-4, and VEGF." (PMID 36679852, 2022). "They differently altered cytokine response in K18-hACE2 mice, and open reading frame 3a (ORF3a) deletion resulted in the lowest IL-6/IL-10 ratio, a marker of cytokine storm in COVID-19." (PMID 35632736, 2022). "This systematic review and meta-analysis aimed to analyze T-cell subsets (CD4/CD8) and IL-10 in severe and fatal cases of COVID-19." (PMID 35572964, 2022). "During COVID-19, many cytokines such as IL-6, IL-10, and TNF-α are markedly higher, whereas T lymphocytes are much lower." (PMID 36278672, 2022). "In the analysis of the antiviral cytokines, only two cytokines were significantly higher in the low-FT3 group, IL-6 (p=0.016) and IL-10 (p=0.015), both defined as markers of COVID-19 severity." (PMID 36440226, 2022). "For instance, the ratios of IL-2/IL-5, IL-2/IL-10, IL-2/IL-9, IL-6/IL-5, IL-6/IL-10 and IL-6/IL-9 were considerably higher in COVID-19 ICU patients as compared to HC subjects (≈8571-, 4800-, 4444-, 378-, 521-, and 172-fold differences respectively)." (PMID 36363785, 2022). "On the other hand, anti-inflammatory cytokines such as IL-1Ra and IL-10 showed a sequential increase in mild-moderate and severe COVID-19, while IL-4 showed a significant increase in mild-moderate COVID-19." (PMID 35529862, 2022). "Generally regarded as an anti-inflammatory cytokine, dramatically elevated IL-10 levels are found in severely affected COVID-19 patients together with pro-inflammatory mediators, a unique feature of COVID-19 related cytokine storm." (PMID 36430566, 2022). "The activation of Tregs in lung tissue is characterized by the release of IL-10, which suppresses excessive inflammatory responses, reflecting the severity of the COVID-19 inflammatory response." (PMID 35615369, 2022). "Accordingly, this systematic review and meta-analysis aims to analyze T-cell subsets and IL-10 levels among COVID-19 patients." (PMID 35572964, 2022). "Data obtained in the present study highlights the use of IL-10 to differentiate secondary bacterial/fungal infections from COVID-19 and/or ECMO associated inflammation in severely ill COVID-19 patients." (PMID 36275812, 2022). "These large-scale data revealed that the serum levels of IL-6, IL-10, IL-2R, TNF-α, IL-1β, IL-4, IL-8, and IL-17 are potential risk factors for severity and high mortality in COVID-19." (PMID 35237162, 2022). "It was observed that supplementing the Janssen COVID-19 vaccine (4 × 109 VP) with a commercial selenium supplement (0.04 mg/kg) and sodium selenite (0.04 mg/kg) increased fold change in transcription of IL-10." (PMID 36679902, 2022). "A previous study reported IL-6, IP-10 and IL-10 of first blood draw as predictors of COVID-19 clinical deterioration while antibody responses negatively correlated with deterioration." (PMID 35177626, 2022). "The pro-inflammatory cytokine levels were elevated in severe COVID-19 patients, but it is observed that both Treg and IL-10-expressing CD4+ T, CD8+ T and NK cells levels were gradually increased from mild to severe patients." (PMID 36110850, 2022).
COVID-19 (continued). "A particular property of the COVID-19-induced cytokine storm compared with that found in SARS-CoV infection is a significant increase in IL-10 in critically ill patients." (PMID 35782361, 2022). "IL-12 (p70) in association with other factors, such as arterial hypertension and anti-inflammatory cytokine IL-10, has shown to be the predictive marker of COVID-19 severity." (PMID 36430621, 2022). "First, due to the limitations of early disease identification and the urgency of controlling COVID-19, patients who were admitted early often lack laboratory data, such as IL-6, IL-10, IFN-γ and viral load." (PMID 35572983, 2022). "Both COVID-19 groups demonstrated a significant elevation (p < 0.001) in IL-1β, IL-4, IL-10, IL-17, and IFN-γ as compared to healthy controls." (PMID 35891209, 2022). "A different investigation with 21 COVID-19 cases found that severe cases had greater levels of IL-2R, IL-6, IL-10, and TNF-α than moderate cases." (PMID 36675695, 2022). "In this study of 90 ICU COVID-19 patients, we evaluated serum levels of four cytokines (IL-1β, IL-6, IL-10 and TNFα) as well as standard clinical and laboratory measurements." (PMID 36451808, 2022). "A significant cytokine storm has been described in patients with severe COVID-19, with elevated serum levels of pro-inflammatory cytokines such as interleukin (IL) 1, IL-6, IL-10, and tumor necrosis factor (TNF)-α." (PMID 35453522, 2022). "In this study, we also found an increase in IFN-γ, TNF-α, IL-1 β, IL-6, and IL-10 in the V-COVID-19 group, which included patients that required hospitalization." (PMID 36497139, 2022). "Herein, we aimed to evaluate the changes in serum IL-6, IL-10, and IL-17A levels and cytometric lymphocyte profiles in 144 COVID-19 patients at admission and after one week, also in relation to steroid treatment before hospitalization." (PMID 35893398, 2022). "Serum IL-10 was significantly higher among COVID-19 active patients compared to unexposed controls and the recovered patients respectively (181±6.14 pg/mL vs 158.80±11.70 pg/mL vs 155.00±14.32 pg/mL, p = 0.038)." (PMID 36094915, 2022). "Similar to high IL-6 and IL-10 activity found in COVID-19 patients, elevated IL-10 plays a key role in the development of pulmonary injury and fibrosis." (PMID 36119044, 2022). "Plasma miR-144, possibly in combination with IL-10 and EGF, emerges as a flexible noninvasive tool for risk-based stratification and mortality prediction of COVID-19 patients." (PMID 36414650, 2022). "Earlier studies had indicated that severely/critically ill COVID-19 cases had elevated serum levels of interleukins (IL-1β, IL-2, IL-4, IL-6, IL-10)." (PMID 36415655, 2022). "Compared to NI subjects, COVID-19 patients had significantly elevated levels of IL-6, IL-10, IFN-γ, CCL5, CXCL9, and CXCL10 and decreased levels of CXCL8." (PMID 36287506, 2022). "Nevertheless, in the present study, IFN-γ, IL-4, IL-5, IL-6, and IL-10 were the only cytokines elevated in patients with COVID-19." (PMID 34987205, 2022). "In “study population B”, 29 COVID-19 patients and 30 NO COVID-19-Vaccinated Controls (NO COVID-19-VCs) were prospectively enrolled for the IL-10 study." (PMID 36148228, 2022). "Some examples include IL10, a tolerogenic cytokine whose expression is increased in COVID-19, and NFKBIz, whose level of expression is decreased." (PMID 36443794, 2022). "Biomarkers such as C-reactive protein (CRP), interleukin (IL)-8, interleukin-10 (IL-10) and tumor necrosis factor (TNF)-α are all considered as diagnostic biomarkers for COVID-19 patients in clinic." (PMID 36343035, 2022). "Plasma levels of TNFα, IL-2, IL-6, IL-8, IL-10 (p < 0.001), IFNγ (p < 0.01), and GM-CSF (p < 0.05) were higher in COVID-19 patients compared to in HCs." (PMID 35625671, 2022). "COVID-19 patients show higher concentrations of IL-2, IL-7, IL-10, G-CSF, IP10 (CXCL10), MCP-1 (CCL2), MIP1a (CCL3) and TNF-α than non-COVID-19 patients." (PMID 35901034, 2022).
COVID-19 (continued). "Patients with low FT3 and older age showed a worse prognosis and higher levels of the COVID-19 severity markers IL-6 and IL-10 than patients with high FT3." (PMID 36440226, 2022). "Extremely high and low levels of IL-10 are considered to play a role in the cytokine storm of COVID-19." (PMID 35860660, 2022). "The first highlight of this study is that IL-10 is a serum cytokine that correlates with post-vaccination neutralization potency in individuals who recovered from COVID-19." (PMID 36366324, 2022). "The evidence also indicated that the severity of COVID-19 increases with the levels of inflammatory mediators including cytokines and chemokines such as IL-2, IL-7, IL-10, and TNF-α in the blood due to COVID-19 infection." (PMID 36091037, 2022). "A pathologic hallmark of severe COVID-19 cases is the onset of inflammatory “cytokine storm”, marked by elevated IL1B, TNFA, CCL2, IL6, MIP1A, and IL10 in the plasma." (PMID 35740365, 2022). "On the other hand, the production of TH2 cytokines (IL-4 and IL-5) and IL-10 was poor or negligible in both post-COVID-19 patients and vaccinated subjects." (PMID 35744768, 2022). "We showed that IL-10 treatment downregulates the production of several immune factors in a similar way, independently of the COVID-19 status." (PMID 36148228, 2022). "IL-10 significantly downregulates several Spike-induced cytokines, chemokines, and growth factors in COVID-19 patients and NO COVID-19-VCs of study population “B”, using a 27-plex multiplex assay." (PMID 36148228, 2022). "A previous study also suggested that IL-6 and IL-10 levels were significantly increased in patients with severe COVID-19 and were strong predictors of severe disease." (PMID 35687545, 2022). "Our findings reveal that the level of CD4/CD8 T-cells and IL-10 are reliable predictors of severity and mortality in COVID-19 patients." (PMID 35572964, 2022). "Based on the COVID-19 cytokine literature, we identified 6 cytokines (IL-1β, IL-2, IL-6, IL-8, IL-10, and TNF-α) commonly found in critically ill COVID-19 patients." (PMID 35033181, 2022). "In the present study, we detected significantly higher serum levels of measured cytokines, chemokines, and inflammatory proteins (IP-10, CRP, IFNγ, IL-10, IL-13, IL-17α, IL-23, and IL-6) in COVID-19 patients than in controls." (PMID 36554094, 2022). "Several studies have correlated elevated serum IL-10 levels with the severity and progression of COVID-19, and it has been described to have a likely predictive value on disease prognosis." (PMID 36363785, 2022). "In comparison, IL-10 was significantly higher in COVID-19 patients who died than in healthy donors, asymptomatic HCWs, and recovered groups." (PMID 35336861, 2022). "COVID-19 plasma exosomes from patients later in their hospitalization induced the production of IL-6, TGFβ, and IL-10 compared with plasma exosomes from early-stage patients or non-COVID donors in Tregs." (PMID 36526691, 2022). "The anti-inflammatory cytokine IL10 and the T cell counts correlate positively to low α-Spike-Ab titers of COVID-19 survivors." (PMID 36293090, 2022). "The results showed an elevated concentration of IL-1β, IL-6, TNF-α, IL-2R, IL-17, and IL-10 cytokines in the serum of COVID-19 patients." (PMID 35842705, 2022). "Possible explanations and implications of the raised IL-10 levels in sufferers from COVID-19 can be discussed in the following manner." (PMID 35891209, 2022). "Our data revealed increased IL10 levels in severe COVID-19 and even higher levels in patients showing an unfavorable disease course." (PMID 34829906, 2021). "The same was true for the chemokine Interferon-y protein 10 (IP-10) which is only transiently increased in the common influenza, while in COVID-19 patients its expression remains constant and, as with IL-6 and IL-10, is correlated with disease severity." (PMID 34072088, 2021).
COVID-19 (continued). "Intriguingly, PD-L1-, ILT-3-, and IDO-1-expressing monocytic MDSC were the dominant producers of IL-6 and IL-10, which correlated with the increased inflammation and accumulation of regulatory B and T cell subsets in severe COVID-19 patients." (PMID 33692788, 2021). "In severe cases, the level of IL-10 was higher than in mild cases, and positively correlated with mortality due to COVID-19." (PMID 34575258, 2021). "Our in vitro study has shown that CVL218 can effectively inhibit the production of several inflammatory cytokines induced by LPS in PBMCs, including IL-6, IL-10, IFN-γ, and TNF-α, which are highly related to the pathogenic characteristics of COVID-19." (PMID 33895786, 2021). "In COVID-19, IL-10 levels were sustained for the duration of the disease, rising as early as the first week in patients who went on to develop severe disease, whereas IL-10 levels only increased in convalescent SARS patients." (PMID 34452323, 2021). "When we analyzed the median proportion of selected cytokines levels (pg/mL) such as: IL-1β, IL-4, IL-5, IL-6, IL-8, IL-10 and TNFα, we observed significant difference between severe COVID-19 and critical COVID-19 patient only for IL-6 level." (PMID 34064802, 2021). "Although the main role of IL-10 is its anti-inflammatory role in the lung, its higher production by Tregs has been correlated with a harsher COVID-19 phenotype and poorer outcomes, making this cytokine an interesting target for more accurate immunotherapy." (PMID 34829906, 2021). "PPI network for the immunity and inflammation cytokines in COVID-19 among R. crenulata targets showed that IL-10, IL-6, IL-1B, TNF-α, CCL2 and CXCL8 were important nodes in the network." (PMID 34313585, 2021). "This particular IL-10 dynamics in COVID-19 markedly differs from SARS where plasma IL-10 remained unchanged in active disease and increased only in convalescent patients." (PMID 33746948, 2021). "In COVID-19 patients, IL-6 concentration directly correlated with IL-10 levels (r = 0.48, p < 0.01) and CRP levels directly correlated with N/L ratio (r = 0.37, p = 0.04)." (PMID 33808205, 2021). "Our biomarker findings are similar to previously reported associations of the levels of several cytokines (e.g., IL-1ra, IL-2, IL-6, IL-8, IL-10, and IP-10) with COVID-19 severity and mortality." (PMID 34386533, 2021). "First, many of the same cytokines that are elevated with high-dose IL-10 administration in the studies discussed above (e.g. IL-4, IL-7, IL-18, IFNγ, TNFα) are also elevated in severe COVID-19 cases in conjunction with elevated IL-10 levels." (PMID 34234779, 2021). "We also highlight the potential utility of therapeutic avenues targeting components of the IL-10 signaling pathway as a viable strategy for restoring IL-10 action in COVID-19." (PMID 34234779, 2021). "IL-10 and IL-10/lymphocyte count at emergency department presentation were described as independent predictors of COVID-19 severity." (PMID 34646263, 2021). "The progress of COVID-19 from mild illness to severe form depends on the circulatory levels of inflammatory cytokines and chemokines such as IL-7, IL-8, IL-9, IL-10, GCSF, GMCSF, TNFα, and VEGFA." (PMID 34786427, 2021). "According to a study by Min, 308 patients with COVID-19 showed that severe cases had a higher level of proinflammatory factors at admissions such as IL-2R, IL-6, IL-8, IL-10, and TNF-α." (PMID 34970527, 2021). "The proportion of IL-10-producing Bregs increased significantly in mild COVID-19 patients, and more so in severe COVID-19 patients compared to healthy donors." (PMID 33692788, 2021). "In contrast, the level of IL-10 in recovered COVID-19 patients was significantly higher in compare to severe cases, COVID-19 patients." (PMID 33914789, 2021). "In the COVID-19 cohort, the systemic CCs IL6, IL1Ra, IL10, TNFa, MCP1 and IP10 had high associations with the BIMs." (PMID 34838058, 2021).
COVID-19 (continued). "CRP was positively associated with IFNγ, IL-2, TNFα IL-1α IFNβ IL-6 IL-17A IL-10, CXCL-10 and VEGF in children with PIMS-TS and COVID-19." (PMID 33813138, 2021). "An increase in the concentration of IL-10 in COVID-19 patients has been demonstrated in an array of studies." (PMID 34766001, 2021). "Based on these observations, immunomodulatory approaches for stimulating adaptive immunity, particularly CD4 T cells, through IL-10 blockade, have potential as a therapeutic approach for patients with COVID-19." (PMID 34251989, 2021). "High levels of anti-inflammatory mediators, such as IL-10 and IL-4, have also been reported in COVID-19 patients, particularly ICU patients." (PMID 33640878, 2021). "In terms of laboratory parameters, elevated inflammatory cytokines and infection-related factors, such as TNF-α, IL-6, IL-10, IL-8, IL-1β, IL-2R, ferritin, hs-CRP and procalcitonin were significantly associated with higher death risk of COVID-19." (PMID 34521370, 2021). "A recent report showed that IL-6 and IL-10 predicted COVID-19 severity confirmed by a ROC analysis (AUC = 0.841 and 0.822, respectively)." (PMID 33668514, 2021). "IL-13 and IL-10 as anti-inflammatory cytokines were also significantly elevated in COVID-19 patients." (PMID 34489933, 2021). "Severe COVID-19 patients have been shown to exhibit higher levels of IL-2, IL-6, IL-10, IL-1, GSCF, MCP-1, TNF-α, and MIP1A." (PMID 35250966, 2021). "Extremely confirmed data from analogous studies with COVID-19 patients reported that the under-expression of IL-10 is mainly due to clones of T lymphocytes." (PMID 33806624, 2021). "There is reported to be a higher level of IL-10 in COVID-19 patients compared to healthy controls, which is correlated with IL-6 concentrations and disease severity." (PMID 35126355, 2021). "The proinflammatory Th1 helper (IL-18, IP-10, MIG, and IL-10) and ARDS-associated cytokines (IL-6, MCP-1, IL-1RA, and IL-8) were increased progressively in patients with increasing severity of COVID-19." (PMID 34938289, 2021). "Administration of Vit D purportedly reverses the induction of interleukin 10 (IL-10)-secreting regulatory T cells in glucocorticoid-resistant patients, a mechanism particularly beneficial in the context of COVID-19." (PMID 35010701, 2021). "In this classification, Severe cases are characterized by high IL-6 and IL-10 levels, both cytokines previously attributed to increase the immunopathogenesis of COVID-19 and predictive value in Severe cases." (PMID 34262570, 2021). "In severely sick COVID-19 patients, cytokine storm syndrome was examined, and it was reported that the extent of interleukins (IL-2, IL-7, IL-10) was high in fundamentally sick patients." (PMID 33907373, 2021). "The high percentage of CD14+CD16+ monocytes in severe COVID-19 patients have been demonstrated in two studies, which are specialized in producing inflammatory mediators including GM-CSF and IL-6, IL-10, and TNF-α." (PMID 33757410, 2021). "In severe/critically ill patients, a dramatic increase of interleukin IL-10 has been described as a crucial feature of COVID-19." (PMID 34646263, 2021). "An upregulation of proinflammatory cytokines including TNF, IL-6, and IL-10 indicates the activation of a specific immune pathway probably leading to a decrease of AQP1 in patients suffering from COVID-19." (PMID 33918079, 2021). "Anti-inflammatory cytokines IL-1 receptor antagonist and IL-10 were both weakly induced in ICI-treated patients with COVID-19, in contrast to control COVID-19." (PMID 34407944, 2021). "It was recently reported that in patients with severe COVID-19 the levels of IL-2, IL-7, IL-10, GSCF, IP10, MCP-1, MIP1A, and TNF-α are dramatically elevated." (PMID 34361736, 2021).